GCG (glucagon)
Diseases named in the same sentence as GCG in open-access papers (continued):
Sharing a sentence is not in itself a finding about the gene and the disease.
type 2 diabetes (continued). "In type 2 diabetes, islets exhibited an increased alpha:beta cell ratio, altered spatial organisation with fewer beta-beta and more alpha-alpha interactions, and a significantly higher proportion of bi-hormonal cells co-expressing insulin and glucagon." (PMID 41059747, 2025). "GLP-1RAs are approved by the U.S. Food and Drug Administration for managing type 2 diabetes and obesity through multiple mechanisms, including enhanced insulin secretion, glucagon suppression, delayed gastric emptying, and modulation of central appetite pathways." (PMID 41303457, 2025). "To better understand the relationship between circulating amino acids and glucagon in obesity and type 2 diabetes, we evaluated circulating amino acid levels in individuals with and without obesity and with and without type 2 diabetes before and in response to a 1-h intravenous glucagon infusion." (PMID 38276866, 2024). "A recent study further demonstrated that the suppression of hepatic glucose production, measured via the clamp technique using tracer glucose, was accompanied by a reduction in glucagon levels and increased insulin secretion in subjects with type 2 diabetes administered 100 mg of vildagliptin." (PMID 40066124, 2024). "Increased plasma levels of glucagon should normally be suppressed by elevated glucose levels; however, patients with type 2 diabetes have increased plasma glucagon levels even at elevated glucose levels and impaired initial suppression of plasma glucagon concentration after oral glucose ingestion." (PMID 39265079, 2024). "An important characteristic of type 2 diabetes is increased plasma glucagon concentrations." (PMID 39265079, 2024). "An ACC inhibitor was tested in a phase II clinical trial for type 2 diabetes and there is evidence that the ACC-alpha pathway in pancreatic alpha cells could be a therapeutic strategy in type 2 diabetes by limiting glucagon secretion." (PMID 38383672, 2024). "There has been increasing interest on the treatment of obesity and type 2 diabetes using glucagon." (PMID 39196987, 2024). "These tissue-level ICWs also suggest that AKH is secreted in a strong pulsatile manner in larvae, a phenomenon similar to the pulsatile release of mammalian glucagon and insulin, which are disrupted in patients with type-2 diabetes, potentially contributing to hyperglucagonemia." (PMID 38947048, 2024). "Numerous studies have described that GLP-1 may be reduced, and glucagon increased, in type 2 diabetes." (PMID 38705923, 2024). "In conclusion, our study supports the involvement of glucagon signalling in metabolic disorders such as type 2 diabetes and MASLD and that increased proglucagon levels may predispose to type 2 diabetes." (PMID 38705923, 2024). "This randomized controlled trial evaluated the immediate effect of RYGB, SG, or PSMF diet alone on beta-cell function in 30 patients with obesity and insulin-treated type 2 diabetes using a euglycemic clamp and a hyperglycemic clamp first in absence and then in the presence of glucagon." (PMID 38589596, 2024). "In conclusion, this comparative study showed modest attenuation of glucagon, adrenaline, and symptom responses to hypoglycaemia in people with type 1 diabetes and preserved responses in longstanding insulin-treated type 2 diabetes, possibly as a consequence of preserved beta cell function." (PMID 38376580, 2024). "The hormone glucagon stimulates glucose production from the liver, which may promote hyperglycaemia if glucagon levels are abnormally elevated, as is often seen in type 2 diabetes and obesity." (PMID 38276866, 2024). "Furthermore, “Glucagon signalling pathway”, “Type II diabetes mellitus” and “Insulin secretion”, all identified here as shared citrullinome pathways, have been identified to be linked target pathways for treatment in neuroinflammation, including in PD." (PMID 39456949, 2024).
type 2 diabetes (continued). "However, at least in regard to glucagon clearance, a recent work reported that this parameter was preserved in patients with type 2 diabetes." (PMID 37030857, 2023). "Exogenous GIP increased plasma glucagon responses to a mixed meal in individuals with type 2 diabetes and apparently led to a transient worsening of plasma glucose excursions, despite some (limited) evidence of insulinotropic activity during the early phase after meal ingestion." (PMID 37430117, 2023). "Some have claimed that glucagon might contribute, at least in part, to the development of type 2 diabetes (review:)." (PMID 37629010, 2023). "Whether glucagon-induced insulin secretion mediated via the GLP1R occurs to a greater extent in type 2 diabetes is unknown." (PMID 37751301, 2023). "Glucagon abnormalities (increased fasting levels and delayed glucagon suppression after glucose intake) has been reported in type 2 diabetes; however, its role in GDM is still unknown." (PMID 36717953, 2023). "In addition to the contribution to hyperglycemia, the failure of α cells to secrete glucagon in response to hypoglycemia is a major limiting factor for optimal glucose control in patients with type 1 diabetes or advanced type 2 diabetes." (PMID 37140984, 2023). "Significantly, those with higher post-meal ratios faced a greater risk of uncontrolled blood sugar, suggesting that an imbalanced high glucagon to insulin ratio could impair glucose control in type 2 diabetes patients." (PMID 37762748, 2023). "The most significant effects of GLP‐1 involve regulating blood glucose levels in individuals with type 2 diabetes by promoting glucose‐dependent insulin release, inhibiting glucagon production, stimulating the growth of beta cells, enhancing insulin secretion, and curbing weight gain." (PMID 38093651, 2023). "Interestingly, the suppression of glucagon by exogenous GLP-1 in type 2 diabetes was antagonised by concomitant administration of GIP, which alone did not significantly affect plasma glucagon concentrations." (PMID 37430117, 2023). "Moreover, there are some studies in which glucagon antagonists were given to patients with type 2 diabetes." (PMID 37629010, 2023). "Although glucagon was discovered over a hundred years ago, glucagon resistance is a recently described concept, and glucagon resistance may be an important factor in the pathogenesis of type 2 diabetes." (PMID 37451484, 2023). "Although post-glucose challenge suppression of glucagon is reduced in people with type 2 diabetes, upregulation of glucagon and inhibition of SRH-induced appetite may be one of the mechanisms of tirzepatide’s action in reducing body weight." (PMID 37367911, 2023). "Indeed, it has been suggested that glucagon elevation occurs in prediabetes and type 2 diabetes to stimulate insulin secretion by the β cell." (PMID 37751301, 2023). "IN THE sophisticated physiological control system that regulates glucose homeostasis, glucagon is the principal hormone responsible for the increase of endogenous glucose production to protect against hypoglycemia, which may lead to coma and death." (PMID 37030857, 2023). "The pathophysiology of type 2 diabetes involves insulin and glucagon." (PMID 35409362, 2022). "When circulating glucose level rises, glucagon secretion is suppressed in healthy individuals, whereas in type 2 diabetes the suppression of glucagon may be impaired." (PMID 35057557, 2022). "Methods for glucagon analysis suffered in the past from lack of specificity and a narrow sensitivity range, which has led to inaccurate results and to the suggestion that type 1 diabetes (T1D) and type 2 diabetes (T2D) patients have elevated fasting glucagon levels." (PMID 35327658, 2022). "Dysregulated glucagon secretion deteriorates glycemic control in type 1 and type 2 diabetes." (PMID 33839150, 2021).
type 2 diabetes (continued). "Nine additional independent markers, not previously associated with type 2 diabetes, showed suggestive associations with reduced glucagon suppression during the first 30 min of the OGTT (P < 1.0 × 10–5)." (PMID 33407418, 2021). "These alterations in glucagon secretion have been proposed to represent a primary defect but may be secondary to other metabolic defects in type 2 diabetes." (PMID 33407418, 2021). "Indeed, inhibition of glucagon signalling by treatment with a glucagon receptor antagonist has shown favourable effects on glucose metabolism in individuals with type 2 diabetes." (PMID 33275161, 2021). "Ten additional variants were suggestively associated with reduced glucagon suppression without conferring increased type 2 diabetes risk." (PMID 33407418, 2021). "However, in our patients with type 2 diabetes, it is more likely that the fasting glucose levels are maintained by (elevated) glucagon levels, as clearly demonstrated in experiments with glucagon receptor antagonists." (PMID 34382579, 2021). "Interestingly, human islets derived from type 2 diabetes individuals exhibited attenuated circadian oscillations, paralleled with reduced insulin and glucagon exocytosis." (PMID 33374803, 2020). "Application of high‐frequency 40 kHz stimulation, which lowered glucagon levels, may have a potential application for the treatment of type 2 diabetes." (PMID 32512650, 2020). "Functional enrichment analysis showed significant enrichment of biological processes that can disrupt the normal glucose, insulin, and glucagon homeostasis in the cell by positively and negatively regulating them leading to the development of type II diabetes mellitus." (PMID 32993798, 2020). "It seems that abnormal glucagon release may also occur in obese subjects ahead of the development of type 2 diabetes." (PMID 32411223, 2020). "Dysregulation of glucagon secretion starts before the development of type 2 diabetes." (PMID 32774668, 2020). "In summary, vagus nerve stimulation modulates glycemia by effecting glucagon and insulin secretions, and high‐frequency 40 kHz stimulation may have potential application for the treatment of type 2 diabetes." (PMID 32512650, 2020). "As such, glucagon‐lowering effects of the 40 kHz blocking stimulation strategy may potentially have useful application to the treatment of type 2 diabetes." (PMID 32512650, 2020). "In particular, applying high‐frequency 40 kHz stimulation lowered glucagon secretions and may have a potential application for developing new treatments of type 2 diabetes." (PMID 32512650, 2020). "However, studies carried out during the last decades suggest that glucagon is also a key regulator of hepatic amino acid metabolism, which, as discussed in the following Section, may be linked with hepatic steatosis/fibrosis and potentially dispose towards the development of type 2 diabetes." (PMID 31284506, 2019). "These are speculative interpretations and future studies are needed to delineate the role of glucagon in the mode of action of this emerging treatment strategy for obesity and type 2 diabetes." (PMID 31443356, 2019). "However, regulation of glucagon secretion by α-cells is impaired in type-1 and type-2 diabetes through pancreatic islet dysfunction." (PMID 31829209, 2019). "So this new peptide from the gut had potential to influence blood glucose in two ways, both by stimulating glucose-induced insulin release and by inhibiting glucagon secretion, both of which would limit hepatic glucose production, the main driver of the fasting hyperglycemia of type 2 diabetes." (PMID 31080438, 2019). "In type 2 diabetes, glucagon dysregulation is as important as insulin dysregulation." (PMID 31357734, 2019). "Finally, the newer class of glucose-lowering drugs for the treatment of type 2 diabetes, sodium-glucose co-transporter 2 (SGLT-2) inhibitors, have been associated with increased plasma glucagon concentrations." (PMID 31284506, 2019).
type 2 diabetes (continued). "In the treatment of type 2 diabetes, there are largely used drugs that act, in part, by inhibiting the secretion or action of glucagon, such as glucagon-like peptide-1 (GLP-1) and GLP-1 receptor agonists, dipeptidyl peptidase-4 inhibitors (DPP-4), and metformin." (PMID 29670459, 2018). "Whether glucagon stimulates tumor growth of CMT93 was examined using type 2 diabetes model mouse allografts." (PMID 29535833, 2018). "In addition, many patients with type 2 diabetes mellitus (T2DM) exhibit elevated glucagon levels and insufficient insulin secretion to control glucose levels." (PMID 29740399, 2018). "Consequently, clinical trials are underway using drugs which block glucagon activity to treat type 2 diabetes." (PMID 29412829, 2018). "Low levels of glucagon and vimentin co-expression, and even lower insulin-vimentin co-expression, have been recently reported in normal human pancreas while a higher co-expression was found in type 2 diabetes." (PMID 29360826, 2018). "Importantly, the clinical results with the antagonists demonstrated unequivocally that inappropriate secretion of glucagon is responsible for a major part of the hyperglycemia of type 2 diabetes." (PMID 28323959, 2017). "Whether personalised treatments of type 2 diabetes based on genotype at either locus may usefully target these changes in glucagon release may be worthy of exploration in the future." (PMID 28343277, 2017). "Besides, in obese adolescents with IGT and type 2 diabetes, ratios of glicentin/glucagon and GLP-1/glucagon at fasting and after OGTT were lower compared to obese adolescents with NGT." (PMID 28736498, 2017). "Type 2 diabetes often presents impaired glucagon suppression by insulin and glucose." (PMID 28881681, 2017). "In addition, other top key connections such as NPY and GCG are also related to both obesity and Type 2 diabetes in humans." (PMID 29156709, 2017). "Furthermore, long-term administration of melatonin resulted in elevation of plasma glucagon concentrations in Wistar rats (WR), whereas in type 2 diabetic Goto-Kakizaki rats glucagon levels were decreased compared to untreated animals." (PMID 28729853, 2017). "In summary, our data suggest that metabolic/hormonal conditions characterizing type 2 diabetes can exert a modulatory effect on the reciprocal regulation of synthesis and secretion of glucagon and GLP-1 in alpha-TC1/6 cells resulting in increased expression of PC1/3 expression and GLP-1 release." (PMID 29121068, 2017). "In this view, glucagon has been recently suggested as the key feature of type 2 diabetes." (PMID 27568179, 2016). "Enhanced glucagon secretion by GIP has been confirmed in patients with type 2 diabetes." (PMID 27483245, 2016). "Correlation of Time50% with AUC−15–120 min-glucagon (type 2 diabetes, r = 0.399, p < 0.05; controls, r = 0.471, p < 0.05) and AUC−15–120 min-GLP-1 (type 2 diabetes, r = 0.437, p < 0.05; controls, r = 0.300, p = 0.107) suggests involvement of glucagon and/or GLP-1 in this process." (PMID 26704625, 2016). "This means that glucagon might be very important for the heart and cardiovascular system in type 2 diabetes." (PMID 27568179, 2016). "Moreover, glucagon levels after rice ingestion and AUC−15–240 min-glucagon were similar in type 2 diabetes and controls." (PMID 26704625, 2016). "Accordingly, suppressive effect of glucagon by DPP-4 inhibitor may mainly contribute to glucose lowering in longer duration of type 2 diabetes patients with decreased insulin secretion capacities." (PMID 25699116, 2015). "In this respect, our data suggests that sustained high levels of glucagon, usually seen in type 2 diabetes, may lead to a decline in hepatic GSH levels that decrease postprandial insulin sensitivity, culminating in a state of insulin resistance." (PMID 25961284, 2015).
type 2 diabetes (continued). "In a recent study we demonstrated that vildagliptin in combination with insulin reduced glucagon levels at hyperglycemia and sustained the glucagon counterregulation to hypoglycemia, which yielded lower glucose levels at hyperglycemia and prevention of hypoglycemia in type 2 diabetes." (PMID 26587020, 2015). "In any case, PASK inhibits glucagon secretion and decreases the blood glucose level; therefore, it is theoretically possible to treat such metabolic diseases as insulin resistance, inadequate insulin secretion, and type II diabetes by effectively regulating glucagon and insulin secretion." (PMID 26371032, 2015). "Given that GIP has a bi-directional glucose-dependent effect on glucagon secretion and has been reported to have a stabilising effect on glycaemia in patients with type 2 diabetes, exogenous GIP could potentially reduce glycaemic variability in this cohort." (PMID 25613747, 2015). "Type 2 diabetes mellitus (T2DM) leads to an elevation in hepatic glucose production driven by insulin resistance in addition to progressive loss of insulin secretion and inappropriate elevations in glucagon concentrations." (PMID 24858947, 2014). "The inhibition of glucagon-GCGR interaction has been reported to control the hepatic glucose overproduction that makes it an attractive therapeutic strategy for the treatment of type II diabetes mellitus." (PMID 25521597, 2014). "The characteristics of AT1R inhibitors in both insulin and glucagon secretion could make it a potential novel therapeutics for the prevention and treatment of type 2 diabetes." (PMID 24371439, 2013). "This could represent improved hepatic insulin sensitivity or decreased pancreatic glucagon release with lowering of high endogenous fasting glucose production, as in type 2 diabetes." (PMID 23349861, 2013). "As the effects of GPR119 activation on islet α-cells are still unknown, glucagon release was also investigated in view of the importance of glucagon for glycemic dysregulation and reduction of glucagon in therapy of type 2 diabetes." (PMID 23781322, 2013). "In the case of islet-derived TTR, it has been theorized that the protein could affect the processing of glucagon, and furthermore that it may influence deposition of islet amyloid, which is found in at least 95% of subjects with Type II diabetes mellitus." (PMID 23840311, 2013). "Since insulin is a physiological suppressor of glucagon secretion, relative insufficient insulin production or declined insulin action in type 2 diabetes may reduce intra-islet insulin action on the suppression of glucagon secretion from the α-cells." (PMID 23316165, 2012). "In type 2 diabetics, the metabolic homeostasis in glucose and glucagon are largely characterized by high α-cell secretion of plasma glucagon, especially in subjects with poorly controlled and insulinopenic status or impaired counter-regulatory response of glucagon to hypoglycemia." (PMID 23226550, 2012). "In addition to failure of β cells to secrete insulin, the α-cell dysfunction in type 2 diabetes seems to result from insulin resistance of these glucagon-producing cells." (PMID 22479612, 2012). "The Gcgr−/− mice and the human patient with Mahvash disease strongly suggest that complete inhibition of glucagon signaling as a therapeutic approach to treat type 2 diabetes may have limited clinical potential due to safety concerns." (PMID 21853126, 2011). "Because the glucagon-producing α-cells harbor the ncNOS enzyme, which apparently is an important regulator of glucagon release, and because raised plasma levels of glucagon is a common feature of and contribute to human type 2 diabetes we also performed parallel studies on glucagon secretion." (PMID 18478125, 2008). "Increased levels of circulating glucagon are a common feature in human type 2 diabetes." (PMID 18478125, 2008).